CCL8 (C-C motif chemokine ligand 8)
Diseases named in the same sentence as CCL8 in open-access papers (continued):
Sharing a sentence is not in itself a finding about the gene and the disease.
liver fibrosis (1 paper, 2026). "Our study establishes that myeloid-specific Tet2 deficiency exacerbates liver fibrosis through the Ccl2/Ccl8–pMDMs–IL-6–HSCs axis, with Tet2−/− pMDMs driving chemokine production, MDMs infiltration, and HSCs activation." (PMID 41474968, 2026). "Third, elevated levels of CCL2 and CCL8 were detected in the serum of elderly liver fibrosis patients carrying TET2 mutations, supporting the clinical relevance of a TET2–CCL2/8 regulatory axis in human disease, which provide a mechanistic basis for the potential clinical application of Bindarit." (PMID 41474968, 2026). "Our study provides novel insights into how myeloid-specific Tet2 deficiency exacerbates liver fibrosis through the Ccl2/Ccl8–pMDMs–IL-6–HSCs axis, offering a potential therapeutic avenue for targeting fibrosis in populations with abundant aging individuals with TET2 mutations." (PMID 41474968, 2026). "Tet2ΔMye exacerbates liver fibrosis through stabilizing Ccl2/Ccl8 mRNAs in pMDMs, creating a chemokine-driven inflammatory loop." (PMID 41474968, 2026). "In conclusion, Tet2ΔMye-induced myeloid hematopoiesis exacerbates liver fibrosis in both young and aging mice through a consistent Ccl2/Ccl8–pMDMs–IL-6–HSCs pathway highlighting a unified therapeutic target for age-associated fibrosis." (PMID 41474968, 2026). "To investigate the role of Ccl2 and Ccl8 in pMDMs intrahepatic infiltration and liver fibrosis progression, we treated mice with Bindarit, a dual inhibitor of Ccl2 and Ccl8, during the construction of liver fibrosis model in Tet2ΔMye mice." (PMID 41474968, 2026). "While our preclinical study demonstrates that Bindarit-mediated Ccl2/Ccl8 inhibition attenuates liver fibrosis in Tet2ΔMye-CCl4 mice, the discordance with cenicriviroc trial outcomes underscores the challenges of clinical application of our findings." (PMID 41474968, 2026). "Inhibition of Ccl2 and Ccl8 by Bindarit effectively suppresses MDMs intrahepatic infiltration and ameliorates liver fibrosis in Tet2ΔMye-CCl4 mice, highlighting the critical role of these chemokines in fibrotic progression." (PMID 41474968, 2026). "To investigate whether Tet2ΔMye in aging hosts exacerbates liver fibrosis through the Ccl2/Ccl8–pMDMs–HSCs axis, we established a competitive bone marrow transplantation (BMT) model using Tet2-deficient BMCs." (PMID 41474968, 2026). "Furthermore, individuals with TET2Mut CHIP exhibited significantly more advanced liver fibrosis and relatively higher levels of Ccl2 and Ccl8 in serum compared with TET2 WT (TET2WT) counterparts, even after adjusting for co-occurring mutations." (PMID 41474968, 2026). "Our findings reveal that Tet2−/− pMDMs are a major source of elevated Ccl2 and Ccl8 in Tet2ΔMye-CCl4 mice, and Tet2−/− monocytes showed an increased expression of Ccr2 and Ccr3, which, thus, created a positive feedback loop that amplifies MDMs infiltration and liver fibrosis." (PMID 41474968, 2026).
migraine (1 paper, 2021). "Levels of IL-1β, CCL3, CCL4, CXCL1, CCL22, and CCL8 were also measured in 55 healthy controls and 64 migraine patients." (PMID 34575163, 2021).
multiple polyps (1 paper, 2021). "CCL8 expression was also significantly lower in patients with multiple polyps." (PMID 34884259, 2021).
nephritis (1 paper, 2023). Inflammation of renal tissue. "It will be interesting to develop an activator of CCL8 expression in podocytes and its receptors on MSCs, which would potentiate the efficacy of MSCs for the treatment of nephritis." (PMID 37567910, 2023). "However, our data imply that CCL8 might have an anti-inflammatory function and be required for MSCs to efficiently ameliorate nephritis." (PMID 37567910, 2023). "Overall, our data suggest that dual regulation of MSCs by up-regulation of CCL8 and down-regulation of CCL5 might work synergistically to ameliorate nephritis." (PMID 37567910, 2023).
oral cancer (1 paper, 2025). "Among the critical findings of this study is the identification of CCL8 as a key marker gene associated with oral cancer." (PMID 40489865, 2025). "Our study goes beyond identifying correlations by demonstrating that specific cytokines, such as CCL2 and CCL8, have a causal role in oral cancer risk, revealing mechanisms behind cancer development." (PMID 40489865, 2025). "Therapeutic Targets: Our identification of cytokines such as CCL2 and CCL8 as key drivers of oral cancer progression presents opportunities for therapeutic targeting." (PMID 40489865, 2025).
peritoneal effusions (1 paper, 2017). "However, in general, MX1, viperin, CXCL10, CCL8, RANTES, KC, MCP1, IL8, GM-CSF and IFNγ were readily detected in FCoV-positive cats whereby MX1 and viperin expression was higher in FCoV-positive cats with peritoneal effusions." (PMID 28388950, 2017).
polyp (1 paper, 2021). A usually exophytic mass attached to the underlying tissue by a broad base or a thin stalk. "The CCL2, CCL7, and CCL8 expression seemed to depend on the polyp location, as the lowest expression ratios were observed for the rectal polyps." (PMID 34884259, 2021). "Detailed analysis of the gene expression in the polyp and normal mucosa showed that the polyp expression tended to be lower in the case of the rectal location (significantly so for CCL8) while being relatively higher in normal mucosa." (PMID 34884259, 2021). "The fold change in CCL2, CCL7, and CCL8 expression was significantly affected by the polyp size." (PMID 34884259, 2021). "Therefore, this study was conducted to assess the suitability of MCP chemokines as targets for chemoprevention by determining the expression patterns of MCP-1/CCL2, MCP-2/CCL8, and MCP-3/CCL7 in colorectal polyps and the chemokine association with polyp potential for malignancy." (PMID 34884259, 2021). "The polyp type had a significant impact on the fold change in CCL2, CCL7, and CCL8 expression." (PMID 34884259, 2021). "Detailed analysis of the gene expression patterns in the normal mucosa and polyps showed that the CCL2, CCL7, and CCL8 expression in the normal tissue was comparable and not affected by the polyp type, contrary to gene expression in the polyps." (PMID 34884259, 2021). "The polyp expression of CCL2 and CCL8 (but not CCL7) was the lowest in the adenocarcinomas." (PMID 34884259, 2021).
prediabetes (1 paper, 2019). "Similarly, IL-33 was inversely correlated with CCL8 in individuals with normoglycemia (r = −0.48; P = 0.04; n = 18) but not in those with prediabetes or T2D." (PMID 31073344, 2019).
Pruritus (1 paper, 2023). Pruritus is an itch or a sensation that makes a person want to scratch. "It was shown that the expression of genes encoding inflammatory mediators such as CCL4, CCL7, CCL8, CCL20, interleukin-19 (IL-19), IL-20, IL-26, IL-36A, IL-36G, and TNF-α) was unique to psoriatic skin with pruritus." (PMID 37834183, 2023).
pulmonary tuberculosis (1 paper, 2012). A bacterial infection that affects the lungs and is caused by Mycobacterium tuberculosis. "We found that CCL8, CCL11 and IP-10 did not significantly differ between pulmonary tuberculosis and tuberculous pleurisy patients." (PMID 23028695, 2012).
Q fever (1 paper, 2017). A bacterial infection caused by Coxiella burnetii. "Gene expression of the chemokines CXCL9, CXCL10, CXCL11 and CCL8 was strongly up-regulated in C. burnetii stimulated PBMCs of chronic Q fever patients, in contrast to healthy controls." (PMID 28793883, 2017). "In whole blood cultures of chronic Q fever patients, production of all four chemokines was increased upon C. burnetii stimulation, but also healthy controls and past Q fever individuals showed increased production of CXCL9, CXCL10 and CCL8." (PMID 28793883, 2017). "Chronic Q fever patients showed increased production of all four chemokines (CXCL9, CXCL10, CXCL11 and CCL8)." (PMID 28793883, 2017).
rectal cancer (1 paper, 2021). A primary or metastatic malignant neoplasm that affects the rectum. "Our findings are consistent with a report that combining CCL8 with CCR5 can treat rectal cancer." (PMID 34844613, 2021).
rectal polyps (1 paper, 2021). "The rectal polyps downregulated CCL2 and CCL7 by 3.1-fold and CCL8 by 5.3-fold, while gene downregulation in the colonic polyps was absent or less substantial." (PMID 34884259, 2021).
rectal tumors (1 paper, 2021). "The CCL8, in turn, was significantly (p = 0.002) more markedly expressed in non-affected mucosa from right-sided tumors, 2.7-fold compared to rectal tumors and 1.8-fold compared to left-sided tumors." (PMID 34885960, 2021).
scrapie (1 paper, 2021). A fatal disease of the nervous system in sheep and goats, characterized by pruritus, debility, and locomotor incoordination. "High-density qRT-PC studies investigating different times of the disease progression revealed overexpression of inflammatory genes Il1rn [IL-1Ra], Ccl8 [CCL8/MCP-2], Tnfsf11 [Tnfsf11/RANKL], and Osm [OSM]) at the preclinical stage in scrapie strain 22L-infected mice)." (PMID 33801117, 2021).
sialadenitis (1 paper, 2021). Sialadenitis is an infection of the salivary glands. "The development of sialadenitis was found to be inhibited in the anti-CCL8 Ab-treated LAT mice when compared with the control Ig-treated mice." (PMID 34391459, 2021).
skin cancer (1 paper, 2025). "Therefore, further studies on targeting Cxcl10 and Ccl8 secreted by macrophages may provide new prospects for skin cancer therapy." (PMID 40282557, 2025).
skin tumors (1 paper, 2025). "Consistent with M2-like macrophages in skin tumors, sub-cluster 2 showed high expression of M2-like macrophage markers, including Mgl2, Cx3cr1, Vcam1, Maf, Ccl8, and Cxcl10." (PMID 40282557, 2025). "Of note, our data showed a higher level of Cxcl10 and Ccl8 in the macrophage population in skin tumors." (PMID 40282557, 2025).
trachoma (1 paper, 2015). "No SNP(PEMMAX < 0.01) was detected in any of thegenes IL8, IL10, CSF2, IFNG, HP, CCL8 or MMP9; all of which had beenpreviously reported to associate with trachoma." (PMID 26616738, 2015).
triple-negative breast carcinoma (1 paper, 2021). An invasive breast carcinoma which is negative for expression of estrogen receptor (ER), progesterone receptor (PR), and human epidermal growth factor receptor 2 (HER2). "Moreover, CCL8 was reported to stimulate fibroblasts in the triple-negative breast cancer subgroup." (PMID 34160019, 2021).
tubular adenoma (1 paper, 2021). A usually polypoid neoplasm arising from the glandular epithelium. "CCL8 was already downregulated in the tubular adenomas (by 1.5-fold) but more markedly so in the tubulo-villous and villous adenomas, in which CCL8 was downregulated by 2.4- and 8.3-fold, respectively." (PMID 34884259, 2021).
ulcerative colitis (1 paper, 2009). An inflammatory bowel disease involving the mucosal surface of the large intestine and rectum. "For instance, the up-regulated expression of chemokines, such as CCL2, CCL3, CCL4, CCL7, CCL8 and CXCL8 has been shown in mucosal biopsies from patients with CD and ulcerative colitis, and this up-regulation correlated with the disease activity." (PMID 19421322, 2009).
Ureteral obstruction (1 paper, 2022). Obstruction of the flow of urine through the ureter. "The immunohistochemical analysis revealed CCL8 and fibrosis- and apoptosis-related markers significantly increased in the unilateral ureteral obstruction model, which agrees with our in vitro findings." (PMID 35203308, 2022).
ZIKV infection (1 paper, 2021). "These authors revealed that the chemokines CXCL10, CCL2, and CCL8 were specifically associated with symptomatic ZIKV infection during pregnancy, and distinct immunoprofiles were detected in different trimesters in ZIKV-infected pregnant women." (PMID 33525328, 2021).
tumor (188 papers, 2010 to 2025). "Ccl8 has been reported to be highly expressed by tumor-associated macrophages promoting an immunosuppressive status." (PMID 40869418, 2025). "Chemokine (C-C motif) ligand 8 (CCL8), abundantly produced by tumor-associated macrophages (TAMs), significantly promotes the invasiveness of GBM cells by stimulating pseudopodia formation." (PMID 40427130, 2025). "Cluster 1 contained genes significantly upregulated in AMPKα1/α2–deficient tumor-infiltrating Treg cells and included genes encoding chemokines (Ccl2, Ccl7, Ccl8), modulators of lipid metabolism (Cd36, Pparg, Lpl, Abca1), and glycolytic enzymes (Hk2, Hk3)." (PMID 40100289, 2025). "In large B cell lymphoma (LBCL), CCL8 was identified as a hub gene, which is involved in several immune activities and correlates with tumor-associated macrophages (TAMs)." (PMID 41155258, 2025). "The most abundant lesion-resident population was LRM4 which was characterized by expression of Ccl8, Mrc1, Gas6, Marks, Cbr, and Folr2, a signature shared with many tumor-associated macrophages (TAM) (19, –21)." (PMID 39255000, 2024). "It has been demonstrated that the glycolysis-induced upregulation of CAXII expression was related to the CCL8 production in tumor-associated monocytes and macrophages." (PMID 37006233, 2023). "In these experiments, we orthotopically transplanted PDGFB-driven primary mGBM tumor cells into the brains of wild-type (WT) mice and mice deficient in Ccl7 or Ccl8/12 expression, a scheme similar to we have shown previously for Ccl230." (PMID 37012245, 2023). "CCL8 was also upregulated in tumor-associated monocytes in a CA12-dependent manner via sustained p38 signaling." (PMID 35362482, 2022). "In a recent laboratory investigation, the data uncovered that CCL8 is a tumor-associated macrophage element that resolves penetration and GBM stemness and has resistance to therapies." (PMID 35328072, 2022). "Additionally, low pH levels upregulate CA XII expression in tumor-associated macrophages, activate NF-κB, and induce CCL8 secretion." (PMID 40422196, 2025). "Furthermore, Ccl8 is also known for its role in the induction of inflammation and is highly expressed in tumor-associated macrophages." (PMID 38933267, 2024). "Together, these data suggest that glycolysis-induced CA12 upregulation might induce CCL8 production by tumor-associated monocytes and macrophages by sustaining the activation of the p38-signaling pathway." (PMID 35362480, 2022). "Likewise, hypoxia-induced ZEB1 promotes CC progression via CCL8-dependent tumor-associated macrophage recruitment (Chen X.-J." (PMID 35769999, 2022). "However, when the spatial localization of CD8+ T cells within the tissue was taken into account, levels of CXCR3 ligands and the CCR5 ligand CCL8 showed a positive association with a high relative T cell infiltration in tumor-rich areas." (PMID 35954489, 2022). "CA12 induces CCL8 production in tumor-associated monocytes and macrophages." (PMID 35362480, 2022). "CCL2 and CCL8 also cause enhanced tumor cell stemness and cancer stem cells self-renewal." (PMID 33182504, 2020). "In vitro studies showed that the exogenous CCL8 blocks the production of this protein in fibroblasts, thus if a CCL8 expressing population grows in the primary tumor, these cells could regulate the chemokine expression of tumor associated fibroblasts." (PMID 26320180, 2015). "Treg-associated chemokine receptor CCR8 ligands, CCL8, CCL16 and CCL18, were also elevated in tumour tissue stellate, epithelial and endothelial cells." (PMID 39915477, 2025). "The TREM2/p-STAT1/CCL8 and PD-L1 axis in TAMs plays a crucial role in tumor progression and resistance to anti-PD-L1 therapy." (PMID 41253786, 2025). "CCL-8 is known for its implication in the migration of monocytes and T-cells, leading to an anti-tumor response." (PMID 40362536, 2025).
tumor (continued). "As a result, M2 macrophages promoted 5-fluorouracil (5-FU) resistance of tumor cells in a mechanism of CCL8 activation of JAK1/STAT3 signaling pathway in tumor cells." (PMID 40361394, 2025). "These KCs are induced by DMBT1-expressing tumor cells, and foster metastatic growth of tumor cells by CCL8-mediated activation of NETosis." (PMID 40796724, 2025). "Then, transcription and protein level of CCL8 were detect in Cohort 1, the results proved that CCL8 was higher in tumor tissue than adjacent normal tissue." (PMID 41253786, 2025). "Ccl8, chemokine ligand 8, secreted by M2-like macrophages, promotes tumor growth and invasion in different cancer types." (PMID 40282557, 2025). "Consistently, histological and IHC staining confirmed that CCL8 rescued the inhibition of tumor formation and apoptosis induction by R428, with cell proliferation largely unchanged." (PMID 39774471, 2025). "We confirmed that TREM2 overexpression promoted CCL8 secretion, which, in turn, contributed to tumor cell proliferation and migration." (PMID 41253786, 2025). "Immune infiltration analysis revealed significant associations between the four genes (BASP1, CCL8, FCGR1B, FKBP11) used for risk stratification and tumor microenvironment composition in KIRC." (PMID 40909125, 2025). "The relative RNA expression demonstrated that Ccl5, Ccl8, Cxcl9, Cxcl10, Cxcl13 and Ccl21 were significantly higher in the 4MOSC1 tumours following oHSV therapy." (PMID 39219056, 2025). "Tumor-associated macrophage (TAM) derived cytokines such as VEGF and CCL8 promote angiogenesis and tumor progression, while NLRP3/IL-1β expression in TAMs is associated with reduced survival and increased lymph node metastasis in HER2+ patients." (PMID 41373809, 2025). "Some studies also report that CCL8 promotes the recruitment of immunosuppressive myeloid populations and supports tumor progression." (PMID 41155258, 2025). "Previous studies have implicated signaling pathways and cytokines such as CCL8, CCL2/CCR2, CSF-1/CSF-1R, STAT3, STAT6, MMPs, AMPK, TLR3, and SIRPα in the regulation of TAMs and tumor progression." (PMID 39781471, 2025). "For example, through CSF-1R signaling, TAM-derived CCL8 enhances tumor cell secretion of colony-stimulating factor 1 (CSF-1), a key factor required for the survival and differentiation of macrophages and dendritic cells." (PMID 41584608, 2025). "CCL8 had previously been shown to be involved in the recruitment of T-regs and the promotion of tumour progression." (PMID 40280979, 2025). "We further observed higher Ccl8 expression in KCs isolated from LvM16 liver metastases as compared to macrophages in liver metastases and in tumor-free livers, and in CD62L+ KCs as compared to CD62L– KCs." (PMID 40796724, 2025). "The mice in the administration clodronate liposomes, recombinant CCL8 and siTREM2 BMDMs group bore larger tumor than those in the administration clodronate liposomes and siTREM2 BMDMs group." (PMID 41253786, 2025). "By binding to CCR1 or CCR5, CCL8 has been shown to enable formation of finger-like projections which increase tumor mobility and, ultimately, invasion." (PMID 41157253, 2025). "The chemokine CCL8 (also known as IL‐8) exerts a tumor‐promoting effect in cancers by enhancing the infiltration of TAMs." (PMID 39499724, 2025). "The activated M2-type tumor-associated macrophages secrete increased levels of chemokine ligand 8 (CCL8), which ultimately induces 5-FU resistance in tumor cells via the JAK/STAT signaling pathway." (PMID 40264038, 2025). "CCL8 is an important chemokine that promotes EMT in tumor cells, enhancing their migration and invasion capabilities." (PMID 40422196, 2025). "Although it is established that CCL8 promotes tumor cell proliferation and migration, its role on the tumor microenvironment following radiotherapy are not yet fully understood." (PMID 38528587, 2024).